PDGFRA (platelet derived growth factor receptor alpha)
Diseases named in the same sentence as PDGFRA in open-access papers (continued):
Sharing a sentence is not in itself a finding about the gene and the disease.
infection (continued). "HCMV TB40-BAC4 was diluted to an MOI ≤ 1 (resulting in less than 64% infection) and preincubated for 2 h at 37°C with various concentrations of the soluble gO receptor PDGFRα-Fc, anti-gB clone C23 or anti-pUL128 clone 4I22." (PMID 33780515, 2021). "Consistent with recent findings for HCMV entry, we have shown that TB40/E infection of human brain organoid involves PDGFRα and EGFR as cellular receptors either directly or indirectly, whereas the infection does not appear to involve cellular integrins." (PMID 33205055, 2020). "The surviving cells following infection were collected for sequence analysis of sgRNA enrichment, and sgRNAs targeting platelet-derived growth factor receptor alpha (PDGFRα) were enriched in cells infected with both trimer-only viruses." (PMID 32587832, 2020). "We next sought to determine if proliferation upon infection in KS-like media was a unique feature of PDGFRA expressing KSHV targets such as hMSCs." (PMID 31881074, 2019). "Viral cancers like KS are the consequence of infection with oncoviruses that evolved powerful mechanisms to persist and replicate through deregulation of host oncogenic pathways—such as PDGFRA signaling—conveying cancer hallmarks to the infected cell." (PMID 31881074, 2019). "We found that in both KSHV-infected hMSCs grown in presence of the inhibitor, PDGFRA signaling was abolished and the proliferation was inhibited shortly after infection." (PMID 31881074, 2019). "In summary, we designed a novel model of “de novo” KSHV oncogenesis based on infection of PDGFRA-positive mesenchymal stem cell progenitors cultured in pro-angiogenic/vasculogenic KS-like growth conditions." (PMID 31881074, 2019). "Given HCMV’s ability to exploit stem-like cells as reservoirs for infection and latency, PDGFRα expression on CSC-like cells may serve a dual function." (PMID 41463341, 2025). "The gH/gL/gO complex binds to PDGFRa, and this is required for efficient infection of fibroblasts." (PMID 40202318, 2025). "Similarly to the gC-II trimer complex, PC plays a vital role in engaging with cell-type-specific receptors for the pH-dependent endocytic route of infection, where PC binds neurophilin-2, replacing PDGFRα as the essential receptor required for infection." (PMID 40432047, 2025). "In sum, PDGFRα+ FC supported both productive infection and latent MCMV persistence in vivo." (PMID 37248241, 2023). "Thus, distinct routes of infection result in differences in MCMV genome distribution in PDGFRα+ FC in the lungs." (PMID 37248241, 2023). "Instead, infection levels depended on the expression of PDGFRα." (PMID 35267456, 2022). "Differential infection levels were highly correlated to PDGFRα expression." (PMID 34575976, 2021). "In addition, the same PDGFRα-derived peptides that were previously identified as inhibitors of cell-free infection have now been found to be effective against cell-associated HCMV, suggesting a common mode of action." (PMID 34578361, 2021). "In infected lungs, PTX3 localized in proximity of PDGFRα+ mesenchymal cells, further supporting its role in this infection is associated with tissue remodeling and not in pro-phagocytic activity." (PMID 34093560, 2021). "Indeed, it is this RTK that has gained more traction as an important mediator of entry, with growing evidence of the importance of gH/gL/gO trimer interactions with PDGFRa during infection of fibroblasts, which is then followed by recruitment of gB." (PMID 29547547, 2018). "Indeed, a subsequent study of glioblastomas revealed that the platelet-derived growth factor receptor A (PDGFRa) RTK was an important mediator of infection." (PMID 29547547, 2018). "Given that PDGFRα increased infection of some cells to 90%, PDGFRα may be very useful in overcoming inefficient HCMV entry (even of lab strains) into the many difficult-to-infect cell types." (PMID 23028311, 2012).
infection (continued). "However, transduction of ARPE-19 cells with PDGFRα rendered the cells highly permissive for infection by both AD169 and TRΔ131, 97 and 98% of the cells were positive for IE-86, respectively." (PMID 23028311, 2012). "In addition, expression of PDGFRα in HUVE cells increased infection of AD169 and TRΔ131 by 100 and 137 fold, respectively." (PMID 23028311, 2012). "In addition, the lower effect of Nrp-2 may be due to the fact that the interaction between the receptor and its ligand occurs within the endosome, so that soluble Nrp-2 cannot inhibit the infection similar to PDGFRα on HELF." (PMID 36901847, 2023). "Importantly, PDGFRα-Fc inhibits infection of various cell types." (PMID 33780515, 2021). "Importantly, PDGFRα-Fc inhibits the infection of various cell types potently." (PMID 33780515, 2021). "Concerning the potential of PDGFRα-derived peptides as a novel option for the development of anti-HCMV treatment strategies, our analysis provides at least proof of principle that the near complete inhibition of cell-associated infection by interference with particle transmission is possible." (PMID 34578361, 2021). "Furthermore, findings on our recently published work using a novel model of de novo KSHV oncogenesis based on infection of PDGFRA-positive mesenchymal stem cell progenitors with rKSHV219 suggest that the deletion occurred in a region of the KSHV genome that is least involved in tumorigenesis." (PMID 32603362, 2020). "To evaluate the role of the gHgLgO – PDGFRα interactions during infection, we infected HFF with WT, gO249, gO117 and ΔgO viruses pre-incubated with increasing concentrations of soluble recombinant PDGFRα-Fc protein." (PMID 40705828, 2025). "Through co‐expression analysis of mCherry and Leydig cell progenitors markers, platelet‐derived growth factor receptor alpha (PDGFRα) and Nestin, we observed a dose‐dependent increase in AAVDJ infection efficiency in Leydig cell progenitors." (PMID 38817099, 2024). "We further show that PDGFRα+ fibroblastic cells are simultaneously permissive to lytic MCMV infection and have a role in viral reproduction during the acute phase of in vivo infection." (PMID 37248241, 2023). "Since gO polymorphisms have been shown to influence the efficiency and selectivity of both cell-free infection and cell-cell spreading of HCMV, we examined gO conservation in 96 strain sequences at the PDGFRα interfaces." (PMID 34700375, 2021). "We found that both PDGFRα and EGFR are important for TB40/E infection of human brain organoid, as siRNA-mediated knockdown of either PDGFRα or EGFR completely abrogated the susceptibility of brain organoids to TB40/E." (PMID 33205055, 2020). "PDGFs compete with the HCMV trimer for PDGFRα binding and block infection, suggesting that PDGF binding to PDGFRα sterically hinders trimer binding or allosterically modulates the trimer binding interface in a non-productive manner." (PMID 32559251, 2020). "To validate ZEB1 and PDGFRA as miR-200 and/or miR-34 targets in a PGL cell context, we enforced miR-200 (LV-200ab/429) or miR-34 (LV-miR-34bc) overexpression by lentiviral infection in PTJ64i cells." (PMID 29305721, 2018). "Endothelial and epithelial cells tend to be negative for PDGFRA and endocytic infection requires the PC in both HCMV and GPCMV." (PMID 41200170, 2025). "Fibroblast entry relies on Trimer binding to platelet-derived growth factor receptor alpha (PDGFR-α) and ectopic expression of this receptor in PDGFR-α non-expressing cells restores infection of HCMV lacking Pentamer." (PMID 33889136, 2021). "For endothelial cells, in which infection does not rely on the interaction of gO with PDGFRα, the inhibitory effect of PDGFRα-Fc is due to inhibition of virus binding rather than penetration, indicating that gO is important for virus adsorption to these cells." (PMID 33780515, 2021).
infection (continued). "In contrast, brain organoids treated with the EGFR- or PDGFRα-specific siRNA showed no or very low GFP fluorescence during the entire 20-day post-infection period and exhibited substantially higher growth kinetics compared to control siRNA-treated organoids." (PMID 33205055, 2020). "We sorted for PDGFRA-positive (Pα(+)S) and PDGFRA-negative (Pα(-)S) MSCs populations, after infection with rKSHV.219 the sorted populations were cultured in mesenchymal stem cell maintenance media (MSC-media)." (PMID 31881074, 2019). "The severe entry defects observed during infection of fibroblasts lacking PDGFRα phenocopy those seen with gO-null mutant viruses, with the residual low-level infectivity being pentamer-dependent." (PMID 30544948, 2018). "Human cytomegalovirus (HCMV) depends on expression of platelet-derived growth factor receptor alpha (PDGFR-alpha) for infection of fibroblasts whereas this cell surface protein is not required for infection of endothelial cells." (PMID 28403220, 2017). "NRP1- and NRP2-targeted knockdown using shRNA infection in these cells significantly decreased PDGFRα and PDGFRβ tyrosine phosphorylation without affecting total PDGFR levels." (PMID 26410366, 2015). "This suggests that PDGFRα may contribute to post-entry signalling events that support infection, rather than serving as a universal entry receptor." (PMID 41463341, 2025). "There may be other receptors for gH/gL/gO since this complex is also important for infection of epithelial and endothelial cells, which may not express PDGFRα (43, 45, –, 51)." (PMID 40202318, 2025). "131stop virus could be completely inhibited with high concentrations of recombinant PDGFRα protein, whereas the pentamer-dependent infection with ΔgO virus could not be inhibited at all." (PMID 40705828, 2025). "When cells are transduced to increase PDGFRα expression, this pathway leads to low pH-independent fusion and productive infection, whether virus particles possess gH/gL/UL128–131 or not." (PMID 23028311, 2012). "Human foreskin fibroblasts (HFF) cells were very efficiently infected with HCMV TR, so that cells transduced with the control Ad-tet-trans exhibited 98% IE-86+ cells using only 1 IU/cell, and this high level of infection was not changed when cells were transduced with PDGFRα or EGFR." (PMID 23028311, 2012). "Therefore, to unambiguously investigate the effect of PDGFRα-Fc on strictly cell-associated growth, we applied it to two recent HCMV isolates or the isolate-like strain Merlin-pAL1502, which form foci of infection in HFF cultures without releasing considerable infectivity into the supernatant." (PMID 34578361, 2021). "The percentage of KSHV de novo infection was similar (80%) in both MSC and KS condition as well as in PDGFRA-negative and PDGFRA-positive cells." (PMID 31881074, 2019). "As previously published, PDGFRα and VEGFR2 were down regulated during WT infection (p-value ≤0.01 for all infections), but their levels are not affected by UL135 or UL138." (PMID 27218650, 2016).
CNS tumors (11 papers, 2010 to 2025). "In contrast, according to the 2021 WHO Classification of Tumors of the CNS, PDGFRA alteration has been reported in 10–15% of GBM cases." (PMID 38255255, 2024). "Clinical trials for pediatric solid tumors, including CNS tumors, are underway with drugs targeting PDGFRA (NCT04773782)." (PMID 37239234, 2023). "Of the three genes examined, overexpression of HOXB13 was unique to MEPN, while overexpression of NEFL and PDGFRα was observed in other pediatric CNS tumors." (PMID 19793339, 2010). "In summary, our findings demonstrate that RIGs are an aggressive, relatively homogenous group of CNS tumors with recurrent amplification of PDGFRA and loss of CDKN2A/B in the absence of somatic H3/IDH hotspot mutations." (PMID 34545083, 2021). "In addition to MEPN and intracranial EPN, comparative gene expression analysis of HOXB13, NEFL and PDGFRα was expanded to include a variety of pediatric CNS tumors." (PMID 19793339, 2010).
gastrointestinal tumors (9 papers, 2008 to 2025). "PDGFRA point mutations (gain of function) were reported to be associated with gastrointestinal tumors." (PMID 38111825, 2023). "Mutated PDGFRA gene is normally more prevalent in gastric GISTs but we had one patient with PDGFRA mutation in colon GIST." (PMID 31653154, 2019). "Constitutive activation of PDGFRα or PDGFRβ is seen in myeloid malignancies as a consequence of fusion to diverse partner genes, and activating mutations of PDGFRα are seen in gastrointestinal tumors (GISTs)." (PMID 19030102, 2008). "Both the PDGFRα V561D and PDGFRα D842V mutants are activating mutations found in gastrointestinal tumors." (PMID 20161827, 2008). "GIST is a rare gastrointestinal tumor originating from Cajal mesenchymal stromal cells, its pathogenesis mainly involves mutations in the c-KIT or PDGFRA genes." (PMID 40837560, 2025). "Epithelioid patterns with platelet-derived growth factor receptor α (PDGFRA) mutations tend to have a favorable prognosis, whereas epithelioid or mixed patterns without PDGFRA mutations, particularly in stomach GIST, have an unfavorable course." (PMID 39246896, 2024). "Although PDGFRA-mutant syndrome features an autosomal dominant pattern of inheritance with high penetrance, the sex distribution of GI tumors is apparently unbalanced, with a 4:11 male-to-female ratio (7/15 considering also pathologically undiagnosed GI tumors)." (PMID 27437068, 2016).
adenocarcinoma (7 papers, 2012 to 2023). A common cancer characterized by the presence of malignant glandular cells. "Mutations in exon 18 were significantly associated only with PDGFRα overexpression (P = 0.024) and mutations in the intron 18–19 were significantly associated with well differentiated adenocarcinoma (P = 0.035)." (PMID 33213472, 2020). "Significant association was observed between PDGFRα overexpression in epithelial and stromal adenocarcinoma cells (P < 10–3)." (PMID 33213472, 2020). "A study was performed with a customized NGS panel (called SiRe) including six genes [EGFR, KRAS, NRAS (NRAS Proto-Oncogene, GTPase), BRAF, KIT Proto-Oncogene Receptor Tyrosine Kinase (KIT)), Platelet-Derived Growth Factor Receptor Alpha (PDGFRA)] for 194 patients with advanced adenocarcinomas." (PMID 33922637, 2021). "In adenocarcinoma, 45% (45/100) of cases showed PDGFRα overexpression." (PMID 33213472, 2020). "This silent mutation was present in the corresponding adenocarcinoma sample too but none of the adenocarcinomas carried gain-of-function mutations in the investigated PDGFRα exons." (PMID 33335133, 2020). "The most mutated immunophenotypes of adenocarcinomas were the undefined (1 KRAS; 2 PIK3CA, and 1 BRAF) and the biliopancreatic (2 KRAS and 1 BRAF), followed by the gynecological immunophenotype (1 case with concomitant KRAS and PDGFRA missense mutation and 1 with PIK3CA mutation)." (PMID 36346458, 2023). "In adenocarcinoma stromal cells, 45% (45/100) of cases showed PDGFRα overexpression, 52% (52/100 cases) showed a low expression and 3% (3/100 cases) showed an absence of PDGFRα expression." (PMID 33213472, 2020). "Indeed, a previous study has shown presence of PDGFRα on the adenocarcinoma A549 cells, that express receptors which are not normally expressed by alveolar epithelial cells." (PMID 24834127, 2014).
lung (6 papers, 2019 to 2025). "Our current study builds on this existing body of work by characterizing significant changes in PDGFRα+ cell number in several models of developmental lung injury." (PMID 38187712, 2024). "Platelet derived growth factor receptor alpha (PDGFRα), which contributes to fibroblast reprograming toward CAFs, plays a significant role in colorectal carcinogenesis." (PMID 31552191, 2019).
hematopoietic neoplasms (5 papers, 2014 to 2025). "Based on these criteria, hematopoietic neoplasms producing eosinophilia are initially classified according to the presence or absence of certain gene variants, including abnormalities (mutant forms) of PDGFRA, PDGFRB, or FGFR1, or the PCM1-JAK2 fusion gene." (PMID 34052871, 2021). "It is worth noticing that although PDGFRα and KIT are expressed in a variety of human hematopoietic neoplasms, the chromosomal region where both genes are located (HSA 4q12) is frequently deleted in hDLBCL, evidence totally in contrast with what observed herein." (PMID 25372838, 2014).
benign tumors (4 papers, 2009 to 2022). "IFPs are rare benign tumors of uncertain histogenesis and were considered reactive processes, but recently, mutations in platelet-derived growth factor receptor alpha (PDGFRA, chromosome 4q12) were described in IFPs located in the stomach and small bowel." (PMID 21403834, 2011). "Differential expression was also observed between LMP tumors and benign tumors/normal ovaries for three out of five genes examined (PDGFRA, SLPI, WNT7A) and between invasive and LMP tumors for the other two genes (C6orf31, GLTSCR2) (Kruskal Wallis p < 0.05)." (PMID 19849863, 2009). "Similar observations of decreased PDGFRA expression in invasive serous tumors compared with benign tumors or normal ovaries have been reported in previous microarray studies." (PMID 19849863, 2009). "Decreased expression of C6orf31, PDGFRA and GLTSCR2 was measured in LMP and invasive tumors compared with high mRNA levels in benign tumors and normal ovarian tissues." (PMID 19849863, 2009).
cardiac disease (3 papers, 2016 to 2021). "Search involving PDGF receptors and cardiac diseases rendered 68 types of cardiac diseases associated with PDGFRα and 106 types with associated PDGFRβ1." (PMID 34513823, 2021). "We hypothesise that these PDGFRα-expressing cMSCs (PDGFRα + cMSCs) are linked to cardiac disease through processes of inflammation and fibrosis, and therefore represent potential therapeutic targets." (PMID 31332256, 2019). "This raises the possibility of therapeutic modulation of PDGFRα + cMSCs in human patients with cardiac disease." (PMID 31332256, 2019). "Our results place PDGFRα + cMSCs as an important cardiac cell population that could be manipulated to enhance current cardiac disease therapeutics." (PMID 31332256, 2019). "As the presence of these cells could be relevant for pathological processes such as fibrosis or valve calcification, future work should explore the role of PDGFRβ+ PDGFRα+ NG2− cells in cardiac disease and in processes involving endothelial–mesenchymal transition." (PMID 27516371, 2016).
retinopathy (3 papers, 2013 to 2021). "PDGF-BB has been reported to be involved in astrogliosis and the formation of proliferative membranes in retinopathy by activating PDGFRα and PDGFRβ." (PMID 33323553, 2020). "Furthermore, systemic administration of imatinib (targeting PDGFRα and β) improved the outcome in a mouse model of oxygen-induced retinopathy—another model of retinal neovascularization." (PMID 33503976, 2021).
kidney diseases (2 papers, 2017 to 2023). "Consuming koumiss has been shown to effectively repair glomerular damage and prevent chronic liver and kidney diseases by increasing platelet-derived growth factor c (PDGF-c) and platelet-derived growth factor receptor alpha (PDGFR-α) expression." (PMID 37927510, 2023).
neurologic diseases (2 papers, 2015 to 2018). "Furthermore, PDGF-CC has been shown to increase the permeability of the blood–brain barrier (BBB), and the role of the PDGFRα/PDGF-CC pathway relative to BBB dysfunction in neurological disorders was recently reviewed." (PMID 29380207, 2018).
brain disorder (1 paper, 2020). A disease affecting the brain or part of the brain. "In addition to the PDGFRα antagonist imatinib, the anti-PDGF-CC mAb 6B3 represents a prospective therapy for brain disorders characterized by a leaky BBB." (PMID 33361796, 2020).